WNT3A (Wnt family member 3A)
Diseases named in the same sentence as WNT3A in open-access papers (continued):
Sharing a sentence is not in itself a finding about the gene and the disease.
breast cancer (continued). "Wnt3a and Wnt3 mRNA were reported to be co-expressed in the embryonal carcinoma NT2 cell line and the breast cancer MCF-7 cell line." (PMID 26369691, 2015). "We thus used microarrays to investigate the expression of 19,738 transcripts following Wnt3a stimulation in two TNBC cell lines, HCC38 and MDA-MB-468, and we report a comprehensive list of genes that are activated or repressed in breast cancer by Wnt3a." (PMID 25848952, 2015). "Together, these data established a Wnt/beta-catenin - collagen axis in breast cancer cells, and demonstrated that Wnt/beta-catenin pathway inhibition by either IWR-1 or CS-E interferes with Wnt3a-mediated induction of Col1a1 expression." (PMID 25090092, 2014). "When co-incubated with supernatants from different breast cancer cell lines, those with high baseline levels of DKK-1 inhibited ALP induction by WNT3A, whereas MCF-7 and T47D cells with low DKK-1 levels had a smaller effect." (PMID 24528599, 2014). "Recombinant WNT3A treatment significantly increased the number of MS in both normal (MCF10A) and breast cancer (MCF7 and MDA-MB-231) cell lines." (PMID 23861811, 2013). "The Wnts that are likely to be involved in mammary specification and early morphogenesis, such as Wnt3a, Wnt6, and Wnt10b, are also genetically altered in MMTV-induced mammary tumours." (PMID 16933995, 2006). "We propose that dysregulation of WNT3A expression in breast cancer leads to more aggressive behaviour, independent of upstream miR‐195‐5p repression after circHSPA8 overexpression." (PMID 40099939, 2025). "Sostdc1 blocks the Smad phosphorylation induced by BMP7 without diminishing BMP2 or Wnt3a-induced signalling in breast cancer cells, indicating that Sostdc1 is a clinically important extracellular regulator of various signalling pathways in breast cancer." (PMID 36338475, 2022). "The IL-8/CXCR2/WNT feedback loop was also observed in the development of chemoresistance and metastasis in estrogen receptor (ER)-positive breast cancer, in which WNT signaling is specifically mediated by WNT3A coupled with SNAI1/nuclear factor (NF)-κB signaling activation." (PMID 34799554, 2021). "In conclusion, we found that a short fragment of POSTN from fibroblasts and breast cancer cells containing exon 17 but not exon 12, binds tightly to wnt3a." (PMID 33919736, 2021). "Wnt ligands, such as WNT3A, WNT9A, WNT11 and WNT5B were highly amplified in breast cancers." (PMID 31462314, 2019). "Wnt3a could downregulate the β-catenin acetylation and promoted the proliferation of human MCF7 breast cancer cells." (PMID 31412883, 2019). "Notably, given that MDA-MB-231 cells were more sensitive to Moracin D than in MCF-7 cells via Wnt3a/FOXM1/β-catenin signaling and activation of caspases, different signaling pathways are expected by Moracin D in two breast cancer cells." (PMID 30201862, 2018). "For example, Wnt3a is highly expressed in human scirrhous gastric carcinoma 44As3 cells with highly metastatic derivatives, advanced prostate cancer cells, and activating transcription factor (ATF3)-induced mammary tumors." (PMID 26369691, 2015). "Moreover, we found that Wnt3a increased expression levels of PLD isozymes in various cancer cells, including colorectal cancer cells (HCA-7, RKO, Colo-741) and breast cancer cells (HS578T)." (PMID 20711340, 2010). "WNT3A, WNT4, WNT6, WNT8B, WNT9A, and WNT10B all are overexpressed in many breast cancer cell lines." (PMID 16933995, 2006). "We observed the downregulation of the Wnt pathway ligand Wnt-3A and the Wnt-dependent transcription factor TCF7L1 in Sdc-1-depleted MCF-7 cells, which is in accordance with our previous observation of a downregulation of the Wnt-coreceptor LRP6 in Sdc-1-depleted breast cancer cells." (PMID 34070901, 2021).
breast cancer (continued). "As shown here, CDK3 exhibited a potent inhibitory effect on Wnt signaling in breast cancer cells through regulating the phosphorylation level of LRP6, the expression of Axin1 and Dvl2, leading to the inhibition of β-catenin, and this process is possibly due to decreased expression of Wnt3a." (PMID 29156693, 2017). "Stimulation of breast cancer cells with Wnt5a-conditioned media does not significantly impact β-catenin phosphorylation, whereas stimulation with media conditioned with the potent canonical Wnt activating ligand Wnt3a significantly reduces β-catenin phosphorylation." (PMID 37147680, 2023). "However, RIPK4 may only play an oncogenic role in Wnt-dependent tumors, since RIPK4 knockdown do not affect Wnt3a-induced β-catenin accumulation in pancreatic, kidney, and breast cancer cells." (PMID 35186499, 2022). "For breast carcinomas, it was shown that neuregulin 1 (ligand for ERBB3 and ERBB4 tyrosine kinase receptors), but not Wnt3A, is indispensable for the isolation and long-term culture and expansion of breast cancer PDOs." (PMID 40863456, 2025). "Proliferation of non-stem breast cancer cells was also affected since depletion of WNT7B/WNT4/WNT3A reduced cell cycle progression while addition of purified WNT7B and WNT4/WNT3A to media had the opposite effect." (PMID 38678032, 2024). "Breast cancer cells that did not respond to the HER2-targeted drug, trastuzumab, showed an upregulation of Wnt3A when compared to normal breast cancer cells." (PMID 34685470, 2021).
prostate carcinoma (42 papers, 2008 to 2025). A carcinoma that arises from epithelial cells of the prostate gland. "Weighted gene co-expression network analysis (WGCNA) suggests a set of five dysregulated hub genes (MAF, STAT6, SOX2, FOXO1, and WNT3A) that played crucial roles in biological pathways associated with prostate cancer progression." (PMID 35719950, 2022). "Quantification by densitometric analysis showed higher levels of Wnt-3a linked to GPCs in prostate cancer cells than in normal cells, especially for DU-145 and LNCaP cells." (PMID 33947326, 2021). "CAFs isolated from Tgfβr2 knockout mice have also been shown to increase tumor growth and proliferation in LNCaP human prostate cancer recombinants in a Wnt3a-dependent manner, indicating TGFβR2-deficient CAFs may contribute to prostate cancer growth in patients." (PMID 36671452, 2022). "SULF1 was demonstrated to antagonize Wnt3A-induced growth and disrupt cellular architecture in prostate cancer models." (PMID 39391236, 2024). "For instance, neutralizing mAbs against Wnt2 and Wnt3A were shown to exert anti-proliferation effects in gastric cancer and prostate cancer models respectively." (PMID 39010070, 2024). "In prostate cancer, miR-15a and miR-16-1 are reported as tumor suppressors and downregulate Wnt3a in prostate cancer cells." (PMID 37190019, 2023). "DVL2 has been shown to enhance the metastatic potential of prostate cancer by upregulating expression of Wnt-3a, AR, and MMP." (PMID 37534375, 2023). "Relevant studies have found that Wnt3a is significantly highly expressed in gastric cancer, prostate cancer and breast tumors." (PMID 35419295, 2022). "We showed through flow cytometry that prostate cancer cells had larger populations of Wnt-3a+ cells than RWPE-1 cells, and DU-145 cells presented a prevalent β-catenin+ population." (PMID 33947326, 2021). "It has been noted that Wnt3a can impact the progression of prostate cancer by enhancing the expression of cytosolic and nuclear β-catenin in addition to enhancing androgen receptor activity or inducing activity in absence of the androgen hormone." (PMID 35201496, 2021). "According to our immunoblotting assays, we were also able to verify that both Wnt-3a and β-catenin were enhanced in prostate cancer cells when compared with normal cells." (PMID 33947326, 2021). "All three prostate cancer cell lines, PC-3, DU-145, and LNCaP, expressed higher levels of Wnt-3a than the normal cell line, RWPE-1 (Fig. 4B1)." (PMID 33947326, 2021). "Our group has also previously shown the relevance of Wnt-3a to the prostate cancer progression, using PC-3 and DU-145 cell lines as a model." (PMID 33947326, 2021). "Firstly, through literature searching, we found TBX2 has been proposed to be a novel therapeutic target and as an upstream of WNT3A in metastasis for skeletal complications in patients of prostate cancer." (PMID 31897234, 2020). "We observed that LEF/TCF reporter activity in prostate cancer cells increased upon stimulation with WNT3a and decreased with CWP232291." (PMID 31387608, 2019). "These miRNAs target several oncogenes such as BCL2, Cycline D1 (CCND1) and WNT3A in prostate cancer." (PMID 28783103, 2017). "The miR-15/16 cluster was found to decrease the expression of β-catenin by targeting WNT3A signaling in prostate cancer." (PMID 28740507, 2017). "Prostate cancer supernatants from the osteolytic PC3 cells potently suppressed the Wnt3a-mediated induction of osteoblastogenesis as seen by decreased levels of alkaline phosphatase (ALP) expression." (PMID 26913608, 2016). "It has been reported that Wnt3a is responsible for stimulating tumor progression in glioblastoma, prostate cancer and colon cancer." (PMID 27329034, 2016). "Up-regulated BCL2, CCND1 and WNT3A which promote tumorigenic features, are the main targets of miR-15a and miR-16-1 in prostate cancer." (PMID 25743273, 2015).
prostate carcinoma (continued). "Increased Wnt3a expression induces prostate cancer LNCaP cell proliferation, neutralizing antibodies to reverse Wnt3a tumorigenesis." (PMID 26369691, 2015). "Wnt3a stimulates tumor progression in glioblastoma, breast and prostate cancers, and malignant mesothelioma." (PMID 25499541, 2014). "Treatment of prostate cancer cells with Wnt3A CM or purified recombinant Wnt3A protein significantly enhanced cell growth and migration, while treatment of prostate cancer cells with the LRP6 antagonist Dkk1 significantly inhibited cell growth and migration." (PMID 23469146, 2013). "In advanced prostate cancer tumors, miR-15a and miR-16-1 levels were found to be significantly decreased with an increased expression of WNT-3a, Bcl2 and CCND1." (PMID 22325146, 2012). "Wnt-3a, Wnt-5a and conditioned medium from prostate cancer cells induced osteoblast differentiation in-vitro and pretreatment of prostate cancer cells with DKK1 diminished osteoblast differentiation." (PMID 22325146, 2012). "Moreover, SULF1 reduced Wnt3a-induced prostate cancer cell growth in tri-culture system consisting of prostate cancer cells, fibroblasts, and macrophages, although further investigation is warranted to determine the clinical relevance of these observations." (PMID 33050237, 2020). "Moreover, prostate cancer cells with a predominantly osteolytic phenotype produced sufficient amounts of DKK-1 to inhibit Wnt3a-induced osteoblastic differentiation in C2C12 cells." (PMID 26913608, 2016). "Moreover, Wnt inhibitors reduce stem cell-like characteristics in prostate cancer cells, whereas Wnt3a stimulates sphere formation and self-renewal." (PMID 26418878, 2015). "Axin blocks Wnt3a’s induction of BMP promoters in prostate cancer C4-2B cells." (PMID 26369691, 2015). "Dvl2 may increase prostate cancer growth and metastatic potential by up-regulating Wnt3a expression." (PMID 26369691, 2015). "Wnt3a causes increased self-renewal and prostasphere size, which is associated with a significant increase in nuclear β-catenin, keratin 18, CD133, and CD44 expression in prostate cancer cells." (PMID 26369691, 2015). "However, other studies have shown that Wnt signaling is involved in prostate cancer growth as was shown by increased sphere formation upon exogenous addition of Wnt3a and anti-tumor effects upon Wnt inhibition." (PMID 25344861, 2014). "For instance, in solid tumors, Wnt3A has been shown to promote the development and progression of colorectal cancer (CRC) 31, prostate cancer 32, liver cancer 33, and lung cancer." (PMID 40657359, 2025). "In prostate carcinoma, the activity of Stat3 located on the Wnt3a promoter is inhibited by TGF-β, resulting in a reduction of Wnt3a levels in tissues and subsequent suppression of tumor progression." (PMID 38886806, 2024). "In prostate cancer, T-box2 (TBX2) was found to promote the transcription of Wnt3a, which, together with the Wnt effector TCF4, is highly overexpressed in osteoblastic bone metastasis." (PMID 36497192, 2022). "CCM1 was silenced in PC3 cells and non-prostate cancer cell lines (U2OS and HT-29), followed by stimulation with WNT3a or PDGF ligand." (PMID 33807895, 2021). "miR-16 is decreased in prostate cancer, whereas the expression levels of its targets, namely Bcl-2, CCND1 and WNT3A, are inversely increased." (PMID 26655091, 2016). "Wnt-3a and Wnt-5a administration or knockdown of DKK-1 induced BMP-4 and 6 expression and promoter activation in prostate cancer cells." (PMID 22325146, 2012). "In advanced prostate cancer, for instance, miR-15a and miR-16 are significantly downregulated, whereas the expression of BCL2, CCND1 and WNT3A is concomitantly upregulated." (PMID 22583478, 2012). "Treating prostate cancer cells with stem cell-like characteristics with WNT inhibitors reduced both the size of tumorspheres and the ability of self-renewal, whereas Wnt3a stimulates them." (PMID 21284870, 2011).
prostate carcinoma (continued). "The Mesd C-terminal region peptide and the full-length Mesd protein block Wnt3a-induced Wnt/β-catenin signaling in LRP5- and LRP6-expressing cells, inhibit Wnt/β-catenin signaling in human breast HS578T cells and prostate cancer PC-3 cells, and inhibit cancer cell proliferation." (PMID 26369691, 2015). "Wnt3a induces BMP-4 and BMP-6 expression and their promoter activation in prostate cancer cells." (PMID 26369691, 2015). "The canonical Wnt ligand Wnt3a and the non-canonical ligand Wnt5a were shown to induce BMP-4 and -6 expression in prostate cancer and to stimulate osteoblast differentiation that resulted in osteoblastic lesion formation." (PMID 36497192, 2022). "Additionally, the treatment of LNCaP human prostate cancer cells with conditioned medium containing the growth factor Wnt3a significantly enhanced cell growth in the absence of androgens, demonstrating that the Wnt pathway may represent a novel mechanism contributing to prostate cancer progression." (PMID 27898031, 2016).
colon carcinoma (40 papers, 2007 to 2025). "Some research indicates that elevated Wnt3a and β-catenin levels in the nucleus are linked to the formation of vascular mimicry in colon cancer." (PMID 40497987, 2025). "WNT3A has been implicated in oncogenesis in several tumors and is associated with proliferation and invasion in colon cancer cells." (PMID 27852072, 2016). "To assess the relationship between VM and Wnt/β-catenin signaling in colon cancer, we determined the expression of Wnt/β-catenin signaling-associated markers, including Wnt3a and β-catenin." (PMID 26266404, 2015). "Studies designed to elucidate the interactions of Wnt3a with other EMT-associated signaling pathways in colon cancer are currently under way." (PMID 25499541, 2014). "Some studies suggest that heightened expression of Wnt3a and β-catenin in colon cancer correlates with VM formation." (PMID 40497987, 2025). "The immunohistochemistry results of this study indicated that signal ligand Wnt3a and key regulatory factor β-catenin of the Wnt/β-catenin signaling pathway were highly expressed in colon carcinoma tissue cells." (PMID 37859826, 2023). "The Wnt/β-catenin signalling pathway serves as a regulatory pathway in tumorigenesis because of its involvement in multiple cellular processes, while Wnt3a is substantially enhanced in colon cancer cells in promoting tumour angiogenesis and metastasis." (PMID 36611811, 2022). "We wondered how LINC01606 and miR‐423‐5p regulated Wnt/β‐catenin signalling in colon cancer and why Wnt3a expression was changed, consistent with our predictions." (PMID 35485210, 2022). "A similar experiment was done with a second set of shRNAs for CD44v6 and WNT3A to confirm that the effects of CD44v6 and WNT3A are specific for FOLFOX stimulated colon tumor resistance." (PMID 36330477, 2022). "To validate the miR‐423‐5p physical interaction between LINC01606 and the Wnt3a 3′UTR in colon cancer, we primarily performed FISH to confirm the subcellular location of LINC01606 in SW480 and HT29 cells." (PMID 35485210, 2022). "Wnt3a is a Wnt protein that activates the canonical Wnt pathway and promotes colon cancer progression, while all the Wnt3a mutations in three DSS-treated mucosae were deletion mutation (one is C deletion and other two is CT deletion)." (PMID 34764977, 2021). "The expression of WNT3A mRNA has notable positive correlation with BRG1 in colon cancer tissues (Pearson Correlation:0.608, P < 0.001, R2 = 0.3699)." (PMID 27852072, 2016). "The expression pattern of WNT3A is consistent with BRG1 in colon cancer tissues and WNT3A expression was inhibited in BRG1 knockdown cells." (PMID 27852072, 2016). "By employing SW-480 colon tumor cells it was shown that under Wnt3a stimulation, β-catenin translocates from the membrane to the cytoplasm and the nucleus where it can mediate the transcription of survival proteins." (PMID 26713600, 2016). "In this study, we revealed a positive correlation between BRG1 and WNT3A expression in colon cancer tissues and cell lines." (PMID 27852072, 2016). "Real-time PCR and immunohistochemistry were conducted to assess the expression of BRG1 and WNT3A in 40 fresh colon cancer tissues and consecutive tissue microarrays, respectively." (PMID 27852072, 2016). "In human colon cancer tissue samples, higher levels of Wnt3a expression and β-catenin nuclear distribution were observed in the VM positive group than in the negative group." (PMID 26266404, 2015). "The effects of ectopic expression of Wnt3a in colon cancer cell line HT29 on the tube-structure forming ability and VM-associated proteins in vitro as well as on the VM forming ability in animal xenograft model were studied." (PMID 26266404, 2015). "Correlation between VM and clinicopathologic characteristics of colon cancer and expression of Wnt3a and β-catenin." (PMID 26266404, 2015).